SIRT1 (sirtuin 1)
Diseases named in the same sentence as SIRT1 in open-access papers (continued):
Sharing a sentence is not in itself a finding about the gene and the disease.
diabetes (continued). "Although previous research has explored the etiology of SIRT1 modulation in ECs, it has not been well studied in diabetes." (PMID 31994599, 2020). "Subsequently, a positive correlation was observed between SIRT1 and TBX-3 mRNA expression levels in the serum of patients with diabetes (R=0.710; P<0.001), suggesting that SIRT1 may positively regulate TBX-3 in endothelial cells." (PMID 32627000, 2020). "Moreover, according to a clinic trial in human and murine models of diabetes, treatment with a PDE5 inhibitor sildenafil induced increment of SIRT1 through a downregulation of the miR-22 expression, resulting in ameliorating visceral adipose tissue." (PMID 31612074, 2019). "Both AMPK and sirtuin-1 have been identified as intracellular energy sensors, detecting and responding to AMP/ATP and NAD+/NADH ratios, respectively, and therefore being activated under conditions of energy depletion and deactivated in diabetes." (PMID 30707256, 2019). "Therefore, in the present article, we discuss the role of SIRT1, SIRT3, and PA on β-cell function and on diabetes." (PMID 31557786, 2019). "Nonetheless, the effect of PRR on AMPK and SIRT-1 under HG or diabetes has not been studied and we plan to do this in the future." (PMID 31800607, 2019). "Thus, designing drugs to enhance SIRT1 and SIRT3 expression and their activity would be useful to protect patients with diabetes and HT against the damaging effect of oxidative stress." (PMID 30736780, 2019). "All these data suggest a relevant implication of SIRT1 in improving GSIS and β-cell function that may result in a potential strategy to help prevent diabetes onset." (PMID 31557786, 2019). "Previous studies have demonstrated that activation of SIRT1 improves diabetes-related chronic kidney disease and nonalcoholic fatty liver disease." (PMID 30988688, 2019). "The negative correlation between SGLT2 and SIRT1 expression under diabetic conditions was further examined using kidney tissue samples from patients with diabetes." (PMID 29717156, 2018). "Moreover, levels of the antioxidant proteins SIRT1 and eNOS were significantly reduced in the aorta of KS−/− mice with STZ-induced diabetes, in contrast to the stimulatory effect of kallistatin administration on SIRT1 and eNOS expression." (PMID 30622668, 2018). "CD1 mice with and without STZ-induced diabetes were randomized to receive the SIRT1 activating compound, SRT3025, or vehicle over 20 weeks." (PMID 30228292, 2018). "In addition, the expression of SIRT1 is significantly lowered and UCP2 increased in the liver of rats with diabetes and NAFLD." (PMID 29949946, 2018). "Similar analyses were performed in the kidneys and retinas of SIRT1 overexpressing transgenic mice with or without streptozotocin induced diabetes." (PMID 25753689, 2015). "Thus given inflammasome activation can impair several metabolically relevant signaling proteins such as Sirt1, additional studies are required to test whether specific inflammasome or caspase-1 inhibitors offer better therapeutic alternatives than IL-1β inhibition as treatment for diabetes." (PMID 23483669, 2013). "Hence, SIRT1 and SIRT3 have been researched in metabolic diseases, such as type 2 diabetes mellitus (DM), fatty liver, and heart diseases." (PMID 24073959, 2013). "In addition, diabetes also led to significant reductions in PPAR-γ and SIRT1 protein levels, and that was prevented by THSG." (PMID 23226517, 2012). "Notably, several studies have also revealed the ability of curcumin in modulating SIRT1-related pathways in non-ocular tissues, such as HUVECs and cardiomyocytes, as well as in an animal model of diabetes." (PMID 40943481, 2025). "When adjusting for age, sex, hypertension, smoking, diabetes, IHD, change in CRP levels and SIRT1 level at baseline in a multivariable model, significantly higher SIRT1 levels could still be observed at 48 months in the active group compared with the placebo group, (p = 0.006)." (PMID 36979007, 2023).
diabetes (continued). "The protein expression of SIRT1/3 was significantly elevated in CF upon HG exposure, yet, only the protein expression of SIRT3 was restored by silencing NAP1L2, indicating that NAP1L2 might affect SIRT3 to affect CF functions in diabetes." (PMID 37993768, 2023). "Given the well-established molecular link between Sirt1 and PPARG signaling and the detrimental role played by PPARG in the context of MCM, we examined PPARG and PPARG-dependent genes LPL, PLIN, CD36, FAS and PPARA in cardiac specimens from diabetics and controls." (PMID 37957697, 2023). "Similarly, SIRT1 was expressed in HCM, non-alcoholic fatty liver disease and Diabetes mellitus." (PMID 36385157, 2022). "Furthermore, when subjected to chronic hyperglycemia in diabetes, low AMPK activity and SIRT1 expression levels may decrease PGC-1α expression and activity." (PMID 36262282, 2022). "Sirtuin 1 (SIRT1) could regulate ACE2 level via AMP-activated protein kinase (AMPK) signals and this role might be beneficial to their protective role against cellular stress in type 2 diabetes mellitus (T2DM), diabetic nephropathy, and myocardial injury." (PMID 33396184, 2020). "Moreover, various PPAR agonists have been proved to prevent diabetes in the non-obese diabetic mouse model, suggesting the therapeutic function of SIRT1-PPARα axis in DM." (PMID 33304318, 2020). "In our study, cotreatment with metformin significantly enhanced p‐AMPK/AMPK ratio and protein expression of SIRT1 in high‐glucose‐stimulated INS‐1 cells, suggesting that the activation of AMPK/SIRT1/PGC‐1α signal pathway may exert a protective effect against diabetes." (PMID 31139382, 2019). "Indeed, data obtained from the retinas of mice with STZ-induced diabetes has shown that resveratrol-induced AMPK activation leads to significant suppression of NF-κB phosphorylation and reverses diabetes-induced sirtuin-1 (SIRT1) deactivation." (PMID 30987058, 2019). "Therefore, the indication for KL1333, as an activator of the SIRT1/AMPK/PGC-1α signaling network, could be extended to aging-related and metabolic diseases such as neurodegeneration, diabetes, and non-alcoholic fatty liver diseases." (PMID 30026729, 2018). "Our results demonstrated that TNK administration improved pre-diabetes and MetS by inducing gene expression involved in fatty acid oxidation in white adipose tissue (WAT), skeletal muscle and liver through the activation of SIRT1 and AMPK signaling in SHR/cp rats." (PMID 25874615, 2015). "Therefore, it is not surprising that downregulation of SIRT1 contributes to medical conditions, such as metabolic syndrome and diabetes, in mice and humans." (PMID 25541949, 2014). "Even though our study suggests that Sirt1 expression and Foxo4 acetylation is altered in diabetes, we have not excluded the possibility that other targets of Sirt1 might also play a role in podocyte apoptosis." (PMID 21858169, 2011). "Besides, SIRT1–endothelial nitric oxide synthase (eNOS) axis, oxidative stress (OS), malondialdehyde (MDA), lipid profile, as well as total antioxidant capacity (TAC) and superoxide dismutase (SOD) are among the indices of endothelial–vascular function impairment due to aging and diabetes." (PMID 36789048, 2023). "Of note, in atherosclerosis, diabetes, and diabetic retinopathy using a SIRT1 agonist, LXR is deacetylated by SIRT1 at a specific conserved lysine (K432 in LXRα and K433 in LXRβ), thereby activating LXR suggesting that SIRT1 may be a potential IBD target to promote LXR-mediated cholesterol efflux." (PMID 36466902, 2022). "Additionally, NaHS eliminated diabetes-induced ER stress by decreasing the expressions of GRP78, CHOP, and cleaved caspase-12 in the hippocampus, while sirtinol abrogated the effects of NaHS, indicating that H2S inhibited diabetes-induced ER stress by promoting SIRT1." (PMID 35806174, 2022). "However, whether SIRT1 can attenuate renal I/R injury by activating the Nrf2/HO-1 signaling pathway in diabetes has not been reported." (PMID 30578379, 2019).
diabetes (continued). "In the present study, we aimed to analyse the levels of SIRT1 and CLDN1 in urine pellets from hypertensive patients with and without diabetes and/or albuminuria to unravel their potential value as non-invasive biomarkers of incipient renal damage." (PMID 32887498, 2020). "Studies have shown that increased FoxO1 plays important roles in antioxidation mediated by Sirt1 and reduced myocardial IRI in mice without diabetes." (PMID 26783539, 2016). "However, in patients with diabetes, resveratrol was able to increase total energy expenditure in the muscle through activation of the AMPK/SIRT1 axis, indicating that SIRT1 alone is perhaps not sufficient to generate an effect." (PMID 33806509, 2021). "Our results are in line with the model in which RSV acts through the AMPK/Sirt1/PGC-1α pathway to modulate the negative effects of HG on BRECs and support future efforts towards the use of RSV to ameliorate the cellular damage induced by diabetes." (PMID 29213353, 2017). "Although miR-217/SIRT1 interaction has not been previously examined in OA chondrocytes, it has been reported in the literature regarding some prevalent age-related pathological/morbid conditions such as CVD, hypertension, atherosclerosis, diabetes, neurodegenerative diseases, arthritis and cancer." (PMID 38136977, 2023).
Insulin resistance (425 papers, 2008 to 2026). Increased resistance towards insulin, that is, diminished effectiveness of insulin in reducing blood glucose levels. "A study showed that extracts from TP flowering tops decreased hyperglycaemia and insulin resistance in T2D rats, associated with increased expression of sirtuin 1 (SIRT1) in pancreatic tissue." (PMID 40887321, 2025). "In contrast, the downregulation of SIRT1 or the inhibition of its activity has been implicated in the pathophysiology of metabolic syndrome determinants, including insulin resistance, type 2 diabetes, and liver lipid accumulation." (PMID 40166461, 2025). "SIRT1 has been strongly associated not only with neuroprotection but also with the amelioration of insulin resistance by silencing the expression of the protein tyrosine phosphatase 1B, a major negative regulator of insulin action." (PMID 40137124, 2025). "On the other hand, reduced levels of sirtuin 1 are associated with glucose intolerance, insulin resistance, and metabolic syndrome." (PMID 40481568, 2025). "The inflammatory response in rostral eWAT was linked to high CLS density and well correlated with SIRT1 heterozygosity and insulin resistance reported in HET mice." (PMID 38255934, 2024). "Reduced SIRT1 activity has been associated with increased hepatic steatosis, insulin resistance, and liver inflammation." (PMID 39459500, 2024). "In recent years, Sirtuin 1 has been shown to be associated with insulin resistance and to be important for glucose-dependent insulin secretion and the protection of pancreatic β-cell mass." (PMID 37854188, 2023). "Meanwhile, studies have found that ALA can significantly increase the activity of SIRT1 and restore insulin resistance caused by high-level glucose induction." (PMID 38111708, 2023). "In cultured 3T3-L1 adipocytes and human adipose tissues, SIRT1 functions as a suppressor of inflammation, which is strongly associated with insulin resistance." (PMID 36747995, 2023). "SIRT1 is also necessary in insulin signaling, and its loss of function is linked with insulin resistance." (PMID 36768465, 2023). "Decreased SIRT1/AMPK activity under hyperglycemia conditions was considered as a cause of higher insulin resistance." (PMID 37630770, 2023). "On the other hand, increased miR-29b-3p in exosomes released by BM-MSC in ageing mice, and consequently inhibition of sirtuin 1 (Sirt1), lead to increased senescence-associated insulin resistance." (PMID 35269453, 2022). "Concordantly, hepatocyte SIRT1 deficiency causes hepatic steatosis, insulin resistance and decreased energy expenditure." (PMID 35228549, 2022). "The inactivation of sirtuin 1 (SIRT1) is connected to the progression of insulin resistance associated with SS." (PMID 35600884, 2022). "MicroRNAs (miRs) are important regulators of inflammation, adipose tissue function, and SIRT1 expression and are implicated in regulating insulin resistance and glucose homeostasis." (PMID 36428537, 2022). "Altered or defective SIRT1 signaling mediated by NAD+ is implicated in insulin resistance and T2D, as SIRT1 positively regulates insulin signaling on multiple levels." (PMID 33609766, 2021). "Hepatic SIRT1 deficiency in mice was shown to increase hyperglycemia, oxidative stress and insulin resistance through impaired AKT/mTOR signaling." (PMID 33806509, 2021). "Studies reported miRNA-377 targeting SIRT1 and reducing its expression in diet obese mice, causing inflammation and insulin resistance in 3T3-L1 cells." (PMID 33123088, 2020). "Residual glucose and insulin signaling-related proteins were detected and the mechanisms associated with the SIRT1/FOXO1 signaling pathway in insulin resistance explored." (PMID 32280711, 2020). "In the same way, the preventive effects of BBR on diet-induced insulin resistance (InsR) was suggested to be linked to sirtuin-1 (SIRT1) and mitochondrial biogenesis." (PMID 32132921, 2020).
Insulin resistance (continued). "Sirtuin 1 (Sirt1) and nicotinamide phosphoribosyltransferase (Nampt) are the rhythmically expressed genes closely associated with insulin resistance." (PMID 32334629, 2020). "PA was used to treat L-O2 cells, as an insulin resistance model, and the SIRT1/FOXO1 pathway-associated proteins were measured." (PMID 32280711, 2020). "This study was designed to evaluate the protective effects of AMPKα and SIRT1 on insulin resistance in PCOS rats, and to illuminate the underlying mechanisms." (PMID 31526389, 2019). "SIRT1 involves cell metabolism, and regulates fat and cholesterol metabolism, with SIRT1 deficiency in mice resulting in insulin resistance." (PMID 29724067, 2018). "Collectively, these findings indicate that overexpressing miR-181a or knocking down SIRT1 in mice causes insulin resistance and impairs glucose homeostasis." (PMID 29207650, 2017). "In our present study, we found that overexpression of miR-377 decreased SIRT1 protein abundance and caused inflammation and insulin-resistance in differentiated 3T3-L1 cells." (PMID 29050301, 2017). "More importantly, we provided evidence that SIRT1 knockdown led to cardiac insulin resistance, as low expression of SIRT1 caused reduced IRS2 expression and impaired insulin signaling in both in vivo and in vitro models." (PMID 28883902, 2017). "Sirtuin 1 (Sirt1), a member of sirtuin proteins family, downregulation is associated with high insulin resistance and loss in mitochondrial biogenesis cells." (PMID 27239252, 2016). "Another study reported that liver-specific Sirt1 deficiency caused an increase in ROS production, which disrupted the mTOR 2/Akt signaling pathway in other insulin-sensitive organs, resulting in insulin resistance." (PMID 27744418, 2016). "Animal studies have demonstrated that SIRT1 deficiency in liver leads to hyperglycemia, oxidative damage and insulin resistance." (PMID 25352008, 2015). "Hypothalamic SIRT1 can improve these disruptions by acting on several targets that cause central leptin/insulin resistance." (PMID 26236282, 2015). "Experimental mice model of hepatic Sirt1 deficiency displayed hyperglycemia, glucose intolerance, hepatic insulin resistance, and oxidative stress in insulin-sensitive organs through disrupted mTorc2/Akt signaling." (PMID 25346724, 2014). "Liver-specific deletion of the Sirt1 gene in mice is reported to cause liver steatosis, insulin resistance, and oxidative stress in various organs." (PMID 23696823, 2013). "The molecules, various resveratrol analogs, caused SIRT1 activation, which has been linked to increased mitochondriogenesis and attenuating insulin resistance in animal models, such as the Zucker fa/fa rats and genetically obese mice (Lepob/ob)." (PMID 21814553, 2011). "We have presented the genome-wide locations for the acetylation of H3K56, a histone modification regulated by CBP, p300 and SIRT1, all of which have been implicated in insulin resistance." (PMID 21655096, 2011). "Similarly, insulin resistance and subclinical atherosclerosis have been associated with low SIRT1 gene and protein expression in PBMCs." (PMID 40760244, 2025). "Additionally, SIRT1 activation was associated with improved insulin resistance, blood pressure, lipid profile, fasting blood glucose, glucose tolerance, and kidney and liver functions." (PMID 40166461, 2025). "SIRT1 has demonstrated efficacy in ameliorating several degenerative conditions associated with neurodegeneration, cancer, and metabolic disorders, including glucose intolerance and insulin resistance." (PMID 38305829, 2024). "Furthermore, studies in prediabetic individuals revealed an association between insulin resistance and reduced SIRT1 expression in subcutaneous fat, accompanied by elevated serum levels of inflammatory cytokines." (PMID 39858569, 2024).